CRP (C-reactive protein)
Diseases named in the same sentence as CRP in open-access papers (continued):
Sharing a sentence is not in itself a finding about the gene and the disease.
COVID-19 (continued). "In conclusion, an advanced age and elevated levels of leukocytes, CRP, GGT, and PCT at admission are predictors for the severity of SARS-CoV-2 infection and can be used to predict the course of COVID-19 at initial stages." (PMID 37363332, 2023). "A recent study enrolled 2765 patients and revealed that a COVID-19 vaccination seemed to induce increased levels of TSH followed by mood disturbance, and pre-vaccine serum TSH, CRP, and anti-TPO should be evaluated." (PMID 38137646, 2023). "Higher qSOFA scores, lower PAFI values, elevated levels of D-dimer and CRP, and low platelet counts were found, findings that reaffirm what has been documented in other studies that patients with AKI and COVID-19 are more inflamed." (PMID 37217840, 2023). "In this context, our results show a statistically significant increase in the expression levels of IL-6, CRP, IDO1 and ACE2 in patients with severe disease compared to patients with mild and moderate COVID-19." (PMID 37715121, 2023). "With respect to Siddiqi and Mehra staging, patient age of older than 75 years, high C-reactive protein (CRP), absolute eosinopenia (AEP), cardiovascular comorbidities, and high ferritin were significant independent predictors for severe COVID-19." (PMID 37766326, 2023). "In our study, the levels of not only CRP but also NLR were statistically significantly different between moderate and severe COVID-19." (PMID 36975366, 2023). "CRP was negatively correlated with IL-6 (r = −0.553, p = 0.011) and positively correlated with MCP-1 (r = 0.389, p = 0.019) in the post-COVID-19 patients." (PMID 37896963, 2023). "Low WBC count, elevated CRP values, elevated ESR, and elevated ALT values were recorded less frequently in children, indicating that children with COVID-19 illness had inadequate immunological responses." (PMID 36949998, 2023). "Markedly increased D-dimer, se-ferritin, hs-CRP levels and LDH activity were present in both COVID-19 patient groups; moreover, D-dimer levels and LDH activity were significantly higher in ICU than in ward patients." (PMID 37629114, 2023). "In our study, higher C-reactive protein, D-dimer, lactate dehydrogenase (LDH) and ferritin levels were observed in COVID-19 patients compared to NC." (PMID 36635274, 2023). "The relative abundance of Alistipes finegoldii, Clostridium innocuum and Ruthenibacterium lactatiformans positively correlated with inflammatory biomarkers (e.g., CRP and WBC) and tended to increase with COVID-19 progression." (PMID 37205106, 2023). "Our study is innovative in characterizing the predictive value of serial measurement in D-dimer, CRP, WBC count, and platelet count on mortality, ICU transfer and OS among hospitalized COVID-19 patients." (PMID 37934759, 2023). "The clinical results of this study showed that the hospitalization in ICU, age, diabetes, PO2, WBC, BUN AST, CRP, and NLR are the most influencing factors on the LOHS with COVID-19." (PMID 37415112, 2023). "Our findings indicated that all patients aged 56 to 69 years with COVID-19 had a significant difference (P < 0.05) in neu, lymph, PLT count, NLR, ESR, Hb, and CRP." (PMID 38025794, 2023). "C-reactive protein (CRP) and interleukin-6 (Il-6) levels correlate positively with COVID-19 severity and mortality." (PMID 37373613, 2023). "Blood levels of sP2X7R correlated with those of the acute phase reactant C-reactive protein (CRP) and were increased in various inflammatory conditions, COVID-19 included." (PMID 37215142, 2023). "Based on these observations, we can conclude that CRP and the majority of inflammatory biomarkers (except sTREM-1, NLR and PLR) had a weak variation by age in COVID-19 patients." (PMID 37388734, 2023). "The values obtained for CRP and PCT are expected and agree with the results of numerous studies on inflammatory markers in COVID-19 patients." (PMID 37790205, 2023).
COVID-19 (continued). "The inflammatory parameters CRP and procalcitonin (PCT) were markedly present in the majority of COVID-19 patients, reflecting hyperinflammation and/or secondary bacterial infection." (PMID 37744227, 2023). "A meta-analysis based on the findings of fundamental and clinical research provided evidence of strong correlation between numerous inflammatory markers, especially C-reactive protein (CRP), interleukin-6 (IL-6), ESR, and severity of COVID-19." (PMID 36982809, 2023). "A higher CT%, leukocyte count, and serum levels of CRP and AST were found in the severe compared to mild forms of COVID-19." (PMID 37373331, 2023). "Gut microbiota composition of COVID-19 patients was found to be connected with plasma concentrations of aspartate aminotransferase (AST), C-X-C motif ligand 10 (CXCL10), CRP and lactate dehydrogenase (LDH)." (PMID 37205106, 2023). "Using open-access databases and clinical retrospective studies, we noticed that serum CRP interacted with circulating megakaryocytes through SPARC and further regulated virus response and systematic inflammation in COVID-19 patients." (PMID 38077346, 2023). "During hospitalization, 12 severe/critical patients with COVID-19 developed multisystem inflammatory syndrome (MIS), which was characterized by elevated inflammatory markers such as CRP, IL-6, and PCT, and the majority of the cases had lymphopenia." (PMID 38274442, 2023). "A body of knowledge also reported that CRP concentration, CK-MB, CK, and LDH levels were higher in COVID-19 patients who died compared to survivors and that these biomarkers were predictors of COVID-19 infection severity." (PMID 37485392, 2023). "In cytokine storms, various acute phase reactants such as C-reactive protein (CRP), ferritin, and LDH are released resulting in multiorgan dysfunction, secondary infection, sepsis, and death in COVID-19 patients." (PMID 37448393, 2023). "It has been also shown that age, serum lactate dehydrogenase (LDH), CRP, red blood cell distribution width (RDW), blood urea nitrogen (BUN), albumin, and direct bilirubin can be used as accurate prognostic indicators for COVID-19 patients." (PMID 38130539, 2023). "In the COVID-19 ARDS group, however, mild but significant positive correlations of endostatin with VE-cadherin, CRP, IL-6, and fibrinogen were detected." (PMID 37283766, 2023). "Here, higher WBC counts with a relatively higher rate of segmented neutrophils on hospital admission, relatively higher WBC counts and CRP levels at the onset of GI symptoms, and prolonged ICU stays were observed among patients with IBS following COVID-19." (PMID 37020263, 2023). "In that study, they found AUC for CRP, procalcitonin, LDH, D-dimer, and albumin in the detection of severe COVID-19 patients to be 92%, 89%, 84%, 83%, and 82%, respectively." (PMID 36919085, 2023). "For CRP, ferritin, SAA1/A2, and S100A12, serum cytokine levels were significantly higher in the COVID-19 group (p<0 · 0001, p = 0 · 0038, p<0 · 0001 and p<0 · 0001, respectively)." (PMID 36590898, 2023). "We detected an increase in the relative expression of the IL-6, CRP, ACE2 and IL-1β biomarkers of 2 mild cases and one moderate case with long COVID-19 compared to healthy individuals." (PMID 37715121, 2023). "Multiple inflammatory factors are significantly increased in COVID-19 patients, such as interleukin-6 (IL-6), tumor necrosis factor-α (TNF-α), and C-reactive protein (CRP)." (PMID 37583958, 2023). "In a prospective study that included 213 COVID-19 patients admitted to the intensive care unit (ICU) the levels of antithrombin, C-reactive protein (CRP); factors XI, XII, XIII; prothrombin and D-dimer were measured." (PMID 37507773, 2023). "LUS has been used to assess lung changes in patients with COVID-19 in intensive care units who were treated with ECMO, and the LUS results have been compared with C-reactive protein (CRP) and ventilator settings." (PMID 37231331, 2023).
COVID-19 (continued). "By contrast, the plasma levels of several markers, including the CRP, D-dimer, LDH and especially ferritin were markedly elevated in COVID-19 patients." (PMID 36635274, 2023). "Routine COVID-19 laboratory assessments, including CBC, CRP, LDH, serum creatinine, and estimated glomerular filtration rates, were performed." (PMID 37108340, 2023). "Some laboratory tests have also been reported to change in COVID-19 patients, including white blood cells (WBCs), NEU ratio, LYM count, C-reactive protein (CRP), erythrocyte sedimentation rate (ESR) and creatinine." (PMID 37396915, 2023). "They discovered that individuals hospitalized with COVID-19 who had a history of VTE, a predischarge CRP level more than 10 mg/mL, or a peak D-dimer level greater than 3 g/mL during hospitalization were more likely to develop new VTE after discharge." (PMID 37362508, 2023). "Diabetes mellitus andhypertension were the most common comorbidities among both nonsurvivors and survivors and higher baseline serum LDH, D-dimer, CRP, ferritin and RBS levels amongmoderate to severe COVID-19 patients." (PMID 37928498, 2023). "The objective of our study is to evaluate the value of daily measurements of CRP and PCT in early identification of ICU-acquired infections in COVID-19 patients." (PMID 37834754, 2023). "The previous study has found higher CD46, CD55, and CD59 levels in monocytes of COVID-19 patients than in healthy people, especially CD55 levels correlated with plasma inflammatory markers such as CRP and serum amyloid A during acute infection." (PMID 36820087, 2023). "Serum semaphorin levels show better predictive values than CRP, IL-6 and LDH for differentiating critical from moderate/severe COVID-19." (PMID 37893159, 2023). "It should be noted that the level of CRP was elevated in both GSM and placebo groups during the study and this effect was possibly confounded by the COVID-19 vaccination of study participants." (PMID 37252684, 2023). "In our COVID-19 patient population, males had higher MAX CRP values (median 16.87 [IQR: 8.35–26.97] mg/dL) than females (12.66 [IQR: 6.42–20.77] mg/dL [p < 0.001])." (PMID 38003780, 2023). "We found a significant increase in other biochemical and hematological parameters for COVID-19 patients including WBC, CRP, PCT, LDH, and ferritin." (PMID 36678211, 2023). "The predictors for in-hospital mortality of COVID-19 patients were identified to be age, congestive heart failure, obesity, COPD, prior stroke, and increased concentration of urea, LDH, CRP, IL-6, troponin I, ALT to AST ratio." (PMID 37624796, 2023). "Age, congestive heart failure, obesity, COPD, prior stroke, and increased concentration of urea, LDH, CRP, IL-6, troponin I, ALT to AST ratio were identified to be the predictors for in-hospital mortality of COVID-19 patients." (PMID 37624796, 2023). "Among COVID-19 patients who were 60 years and older, PLT, DBIL, iBIL, and CRP were significantly higher than in younger patients who were less than 60 years old." (PMID 37223120, 2023). "This study highlighted the significance of biomarkers WBC count, MPV, PWD, platelet count, NLR, serum ferritin, D-dimer, CRP, IL-6, LDH, and PCT levels in predicting the severity of COVID-19 patients." (PMID 37016651, 2023). "Plasma biomarkers such as CRP and PCT are insufficiently sensitive or specific in predicting the onset of severe septic shock, ARDS and COVID-19-related acute viral septic shock in these critically ill patients." (PMID 37391718, 2023). "Hs-CRP, Ferritin, LYM values, and NLR decreased after treatment in patients with COVID-19 (p = 0.001, p = 0.001, p = 0.001, p = 0.012, respectively)." (PMID 36867280, 2023). "Il-6, D-dimer, VWF, CRP, and PCT seem to be good COVID-19 biomarkers that are easy to perform in clinical practice." (PMID 37489362, 2023).
COVID-19 (continued). "The present study aimed to determine the cut-off value for C-reactive protein (CRP) and the neutrophil-to-lymphocyte ratio (NLR) for predicting bacteraemia in patients with COVID-19." (PMID 37939245, 2023). "Inflammatory markers, e.g., CRP, IL6, have been proven to significantly increase with disease progression in COVID-19 patients and can be used to differentiate the severity of patients’ condition." (PMID 37762549, 2023). "The results showed that the levels of WBC, neutrophil, PCT, CRP, NLR, PLR, CLR, D-dimer, LDH and hs-TNT, SCC were significantly higher in severe COVID-19 patients than those in mild COVID-19 patients." (PMID 37860066, 2023). "Significantly higher plasma glucose, neutrophil-to-lymphocyte ratio, platelet count, C-reactive protein, and serum ferritin were seen in CAM patients during their hospitalizations for COVID-19." (PMID 36573628, 2023). "Inflammatory markers, such Hs-CRP, Ferritin, LYM, and NLR, are important indicators used both to show the severity of COVID-19 and to evaluate the prognosis of the disease." (PMID 36867280, 2023). "In our earlier analysis, ANC, CRP, D-dimer, and BUN were shown to be independent predictors of COVID-19-related mortality." (PMID 37041917, 2023). "Following this, the present study results indicate that D-dimer, Hs-CRP, ferritin, procalcitonin, and CPK were significantly elevated in severely ill patients and critically ill patients compared to moderately ill COVID-19 patients." (PMID 36766892, 2023). "Few investigations like CRP, procalcitonin, IL-6, ESR, ferritin, chest X-ray, and CT scan are done to assess the severity and clinical score of COVID-19 patients." (PMID 36819455, 2023). "Many studies have pinpointed various prognostic markers, including D-dimer, C-reactive protein (CRP), lactate dehydrogenase (LDH), and high-sensitivity cardiac troponin, in serum of COVID-19 patients with poor outcomes." (PMID 38027038, 2023). "The most valuable predictors of COVID-19-related death at the time of the ICU admission were CAD/CHF, stage 3–5 CKD, BUN, and CRP." (PMID 36826535, 2023). "The aim of this study was to analyze the serum concentration of interleukin-6 (IL-6), C-reactive protein (CRP), D-dimer, lactate dehydrogenase (LDH), ferritin, and procalcitonin in COVID-19 patients with different forms of the disease." (PMID 37239895, 2023). "Our study showed that COVID-19 AIS patients had higher initial NIHSS, higher CRP, and lower lymphocyte count." (PMID 36862706, 2023). "ICU COVID-19 patients showed higher levels of NET markers (MPO, MPO-DNA, and histone H3) and cell-free DNA that were strongly correlated with CRP, D-dimer, and LDH, while the expression of histone H3 was associated with thromboembolic events." (PMID 37896963, 2023). "This study aimed to evaluate the levels of immunological biomarkers such as CRP, C3, C4, IL-8, IL-10, IL-12, TNF-α, and IFN-γ in patients with COVID-19 and bacterial pneumonia." (PMID 38585537, 2023). "Data revealed the expected increasing effect of COVID-19 for ALT, GGT, LDH, ferritin, and CRP in the deceased group and for IL-6 in the ICU individuals." (PMID 36831321, 2023). "Of note, especially when looking at the multivariate analysis of our study, high CRP does commonly occur in cancer patients, which implies that it might be questionable whether or not it should be considered to be an independent prognostic factor in cancer COVID-19 patients." (PMID 37643201, 2023). "The present study therefore aimed to determine the cut-off value for CRP and NLR for predicting bacteraemia in patients with COVID-19." (PMID 37939245, 2023). "Moreover, CRP levels above 80 mg/dl could differentiate mild COVID-19 cases from bacterial pneumonia, while levels above 100 mg/dl were significant in distinguishing moderate COVID-19 cases from bacterial pneumonia." (PMID 38585537, 2023).
COVID-19 (continued). "The receiver operating characteristic curve found age, urea, uric acid, CRP, ferritin, IL6, and LDH with the highest odds of predicting ICU admission for COVID-19 patients." (PMID 36819455, 2023). "In accordance with the previous studies, Hs-CRP, Ferritin, LYM values, and NLR were higher in patients with severe COVID-19 than patients with mild/moderate COVID-19 before COVID treatment." (PMID 36867280, 2023). "The COVID-19 group had higher values of leukocytes, neutrophils, neutrophil/leukocyte ratios, ASL, ALT, LDH and CRP, and lower values of lymphocytes compared to the control group." (PMID 36676134, 2023). "Our aim was to assess the value of daily measurements of C-reactive protein (CRP) and Procalcitonin (PCT) in the early identification of ICU-acquired infections in COVID-19 patients." (PMID 37834754, 2023). "In the present study, age (>58), urea (>34), CRP (>71.5), ferritin (>371), IL-6 (>6.4), and LDH (>391) showed the highest odds of predicting ICU admission amongst all other parameters in COVID-19 patients." (PMID 36819455, 2023). "Patients with attenuated postconvalescence richness exhibited higher levels of C-reactive protein (CRP) and illness severity during the acute phase, indicating a strong correlation between inflammatory response and gut dysbiosis in COVID-19." (PMID 37895405, 2023). "A clinical trial found that quercetin is safe and effective in lowering the serum levels of ALP, q-CRP, and LDH as critical markers involved in COVID-19 severity." (PMID 37274117, 2023). "A 2021 study found higher CRP levels in patients with both EBV and COVID-19 compared to patients with only COVID-19." (PMID 37364815, 2023). "The biochemical indices of inflammation include C-reactive protein (CRP), D-dimer, serum ferritin, hemoglobin (Hb), interleukin-6 (IL-6), lactate dehydrogenase (LDH), which are routinely done in COVID-19 patients admitted in AIIMS Patna." (PMID 37016651, 2023). "Even though our findings resulted from a monocentric study and the time frame for patient enrollment was limited, they highlighted the pivotal role of IL-6, LDH, CRP and PCT in predicting mortality for hospitalized COVID-19 patients." (PMID 36836679, 2023). "Expectedly, serum inflammatory factors (NLR, PLR, LMR, CLR, PCT, CRP), coagulation markers (APTT, PT, TT, FIB, D-Dimer), Myocardial damage markers (hs-TNT, LDH) were significantly increased (P<0.05) in severe COVID-19 patients." (PMID 37860066, 2023). "We found a higher CT%, as well as serum levels of CRP, neutralizing antibodies to the SARS-CoV-2 Omicron strain, and total anti-SARS-CoV-2 antibodies in moderate compared to mild forms of COVID-19." (PMID 37373331, 2023). "A recent study showed that CRP and novel markers such as CRP-to-lymphocyte ratio (CLR), neutrophil-to-lymphocyte ratio (NLR) and platelet-to-lymphocyte ratio (PLR) can all predict oxygen requirement in COVID-19 patients." (PMID 37373898, 2023). "Many inflammatory markers such as neutrophil-lymphocyte ratio (NLR), D-dimer, serum ferritin, C-reactive protein (CRP), and interleukin-6 (IL-6) were used for the diagnosis and prognosis of COVID-19." (PMID 37575788, 2023). "For COVID-19, the biomarkers are lymphocytes (lymph), lactic dehydrogenase (LDH), high-sensitivity C-reactive protein (hs-CRP), indirect bilirubin, creatinine, etc." (PMID 36873902, 2023). "In non-survival patients, WBC count, neutrophil count, D-dimer, CRP, ferritin, troponin T, ALP, and creatinine levels were significantly higher compared with survival COVID-19 patients." (PMID 38130539, 2023). "In conclusion, the maximum CRP value evaluated over the first 5 days of hospital admission can be used as a rapid and inexpensive approach for clinicians to efficiently triage patients to predict COVID-19 severity, independent of known risk factors such as patient age, sex, and BMI." (PMID 38003780, 2023).